SPP1 (secreted phosphoprotein 1)
Diseases named in the same sentence as SPP1 in open-access papers (continued):
Sharing a sentence is not in itself a finding about the gene and the disease.
cancer (continued). "By performing qRT-PCR, we observed that cancer cells exposed to SPP1 exhibited a significantly increased gene expression in EMT-related molecule CD44 and glycolytic genes including SLC2A1 and ENO2 at 48 h." (PMID 34676217, 2021). "Secreted phosphoprotein 1 (SPP1) plays a pivotal role in the growth, proliferation, migration, and apoptosis of cancer cells." (PMID 34262941, 2021). "Overexpression of SPP1 was found to enhance cancer cell proliferation, migration and invasion, which were concomitant with downregulation of epithelial biomarkers and upregulation of mesenchymal biomarkers." (PMID 33996808, 2021). "Taken together, our results of the paracrine interactions analysis and in vitro experiment highlight the cancer-promoting role of SPP1 and TNFSF12 signaling." (PMID 34676217, 2021). "In cancer research, the published literature has provided a basic outline of SPP1 biofunctions in tumorigenesis and processes." (PMID 33954053, 2021). "Secreted phosphoprotein 1 (SPP1) gene encodes for the protein Osteopontin, which is a phosphorylated protein of the ECM, that has a dominant role in B and T cell control, in cancer development and is a gene relevant for ECM." (PMID 33648423, 2021). "Upregulated expression of SPP1 has been identified as a candidate to trigger the release of these MMPs to induce metastasis of cancer cells via NF-κβ." (PMID 34946170, 2021). "The expression level of SPP1 is elevated in cancers, particularly those that spread preferentially to the skeleton." (PMID 34209195, 2021). "We observed significant deregulation of 14 cancer-related IPA pathways for which pathway directionality was known in HPDE6c7 SPP1 KO lines vs. HPDE6c7 scr gRNA controls." (PMID 34009124, 2021). "Several recent studies focused on the expression and predictive value of SPP1 in various cancer cells." (PMID 34977258, 2021). "The aberrant expression of secreted phosphoprotein 1 (SPP1) is involved in radiosensitivity in a variety of cancers." (PMID 34367279, 2021). "The results showed that levels of SPP1 expression in cancer tissues were higher than that in non‐smoker controls (P = 0.007) and smoker controls (P = 0.002)." (PMID 33626243, 2021). "It is reasonable to believe that the effects of SPP1 on these common genes promote immune infiltration and cancer progression." (PMID 33324676, 2020). "The present work systematically assessed SPP1 level together with the correlation between SPP1 and prognosis in various human cancers." (PMID 33324676, 2020). "These experiments reveal the robustness of our results and overexpression of SFN and SPP1 in HCC promotes cancer cell proliferation." (PMID 33221766, 2020). "Based on Kaplan-Meier plotter and the PrognoScan database, we found high SPP1 expression was significantly correlated with poor survival in various cancers." (PMID 33324676, 2020). "Abnormal expression of SPP1 was found in numerous cancers and also has potential correlation with cancer prognosis." (PMID 32641130, 2020). "The high expression of SPP1 in a variety of cancers suggested that it was related to clinical prognostic outcome." (PMID 33324676, 2020). "More and more studies have shown that SPP1 is closely related to the migration and metastasis of the malignant tumors." (PMID 32595698, 2020). "For better determining the SPP1 prediction ability for diverse cancer types, PrognoScan was adopted for evaluating how SPP1 level affected OS and RFS." (PMID 33324676, 2020). "The expression of 22 common genes and SPP1 were classified as high or low SPP1 expression group in four types of cancer and showed in the heatmap." (PMID 33324676, 2020). "Subsequently, this study investigated the SPP1 prediction significance for cancers by the K-M plotter and PrognoScan databases." (PMID 33324676, 2020). "Studies have found that SPP1 can promote the proliferation, migration and invasion of malignant tumor cells and inhibit cell apoptosis, leading to poor prognosis in certain tumors." (PMID 33193731, 2020).
cancer (continued). "NSCLC ranked ninth among cancer cell lines based on the SPP1 expression according to the data from CCLE database." (PMID 32595698, 2020). "Patients in four cancers were classified as high (red) or low (green) SPP1 expression group based on the median expression of SPP1." (PMID 33324676, 2020). "Subsequently, this study examined the SPP1 prediction significance for different cancer types based on the K-M plotter." (PMID 33324676, 2020). "The present work suggested that the up-regulated SPP1 level was related to the dismal prognostic outcome in virous malignant tumors." (PMID 33324676, 2020). "The different SPP1 expression in cancer compared with non-carcinoma tissues was found by the box plots, and the different expression levels were statistically significant upon Wilcoxon test." (PMID 33324676, 2020). "The lower SPP1 levels only appeared in the kidney renal clear cell carcinoma (KIRC) relative to the non-carcinoma samples." (PMID 33324676, 2020). "Some studies suggested that SPP1 played an important role in the progression and metastasis of several types of cancers." (PMID 31921672, 2019). "Altogether, these reports suggest that a feedback loop exists between NRF2 and SPP1 in cancer cells." (PMID 31884422, 2019). "Of those modulated genes, SPP1, IL1RN, IL1A, TNFSF13B, OSM, and CSF3 had the most clinical relevance, as their high expression was associated with poor cancer patient overall survival." (PMID 31022845, 2019). "SPP1 has been reported to enhance cancer cell survival, angiogenesis, and inflammation, while also promoting metastasis by favoring epithelial-to-mesenchymal transition." (PMID 31849319, 2019). "Of note, mRNA levels of PKM1, Hbb-b2, and Spp1 were significantly elevated in both colon polyp tissues and cancer organoids from colon polyps from PKM2ΔLgr5-Tx mice." (PMID 30996297, 2019). "Pathway analysis revealed that SPP1 overexpression affected the expression levels of BRCA1 and CDC20, which have been reported to be associated with several cancers types." (PMID 30517191, 2018). "Despite numerous reports regarding SPP1 up-regulation in many cancers, there is a scarce information regarding the transcriptional regulation of SPP1, in particular in cancer stem cells." (PMID 28030801, 2017). "Exon array analysis identified a mean expression level of 12.06 (log2) for SPP1 in malignant tumours and a mean expression level of 5.65 (log2) in benign plexiform neurofibromas." (PMID 25884485, 2015). "In conclusion, our data demonstrate that the loss of CBX7 associated to the increase of HMGA1b during carcinogenesis would contribute to cancer progression through the transcriptional deregulation of the SPP1 expression." (PMID 25595895, 2015). "In conclusion, the loss of CBX7 expression associated to HMGA1b over-expression contributes to the positive regulation of the SPP1 gene expression in cancer." (PMID 25595895, 2015). "SPP1 overexpression in cancer cells led to the down-regulation of E-Cadherin and up-regulation of N-Cadherin and Slug at both the mRNA and protein levels, and up-regulation of Vimentin and Snail at the mRNA level." (PMID 26565418, 2015). "SPP1 induced the nuclear localization and activation of β–catenin in epithelial and cancer cells, resulting in an EMT phenotype." (PMID 26565418, 2015). "Osteopontin (OPN), a glycoprotein also named Secreted Phosphoprotein 1 has been implicated in 3 types (EMT associated with migration of cancer cells (metastasis) is referred as Type III." (PMID 25932287, 2015). "On the other hand, SPP1, SPINK1 and STEAP1 are proteins that are up-regulated in several human carcinomas and their overexpression is also associated to cancer progression." (PMID 24865347, 2014). "The human lung tissue QRT-PCR array assay of 24 paired mRNA samples of cancer and adjacent normal lung tissues was used to validate two AC discriminating genes SPP1 and CENPA." (PMID 22369099, 2011).
cancer (continued). "The tissue microarray analysis further demonstrated that this increased mRNA expression level of SPP1 was significantly correlated with protein level in cancer patients." (PMID 17989776, 2007). "Tissue microarray analysis (TMA) was also performed for three randomly picked common cancer genes (SPP1, BID and CLU) to determine if mRNA changes were correlated with changes in protein expression in cancer patients." (PMID 17989776, 2007). "SPP1 has become of interest in tumorigenesis, and expression of the protein has been observed in human cancer." (PMID 17022822, 2006). "Understanding the spatial distribution and functional implications of SPP1‐expressing macrophages interacting with cancer cells within the TME could provide valuable insights into the mechanisms underlying CCRT resistance in hypopharyngeal SCC." (PMID 41466485, 2026). "We find elevated interactions between SPP1+ macrophages and cancer cells in CCRT‐resistant tumors." (PMID 41466485, 2026). "The ELISA assay demonstrated that knockdown of ENO1 could decrease the SPP1 secretion of cancer cells, while overexpression of SPP1 in ENO1-KO cells could rescue it (Additional file3H, I)." (PMID 40665335, 2025). "In particular, SPP1+ macrophages showed significant variation across these cancer types." (PMID 39999031, 2025). "SPP1 expression was higher in hypoxia-high macrophages in pan-cancer." (PMID 41425545, 2025). "Thus, SPP1+ TAMs constitute a clinically relevant subset that underscores the complexity of macrophage functions in cancer." (PMID 41425545, 2025). "The CXCL9/SPP1 axis has significant prognostic implications in cancer, and targeting factors that influence this axis may provide therapeutic benefits." (PMID 41391064, 2025). "Other functions of the SPP1 protein include bone remodelling, anchoring osteoclasts to the bone mineral matrix, regulation of the innate and adaptive immune systems, cell differentiation, cytokine production, and cancer progression, among others." (PMID 40395129, 2025). "Silencing OCT4A reduces SPP1 expression and attenuates cancer cell migration." (PMID 40559389, 2025). "SPP1, also known as osteopontin (OPN), is highly expressed in various malignant tumors." (PMID 41181127, 2025). "The continued development of strategies to target SPP1+ macrophages whether through direct SPP1 neutralization, blockade of their pro-tumoral functions, or disruption of their survival signals represents an emerging frontier in cancer therapy." (PMID 41425545, 2025). "The ELISA assay showed that BMDMs or THP-1 cells from WT cancer cells could secrete higher SPP1 than those from ENO1-KO cancer cells." (PMID 40665335, 2025). "In this study, we have conducted a detailed investigation of the role of SPP1 in four particular types of cancer in humans, breast, prostate, renal and skin, which not only have a higher global prevalence but also wherein the role and effects of SPP1 have already been extensively studied." (PMID 39857756, 2025). "HCC patients with increased numbers of cancer stem cells also displayed an accumulation of a HIF-1α-driven SPP1+ macrophage subset characterized by the expression of MMPs (MMP9, MMP12, and MMP17), which may enhance cancer epithelial‒mesenchymal transition." (PMID 40721870, 2025). "Previous studies showed that M2 TAMs could secret SPP1 protein to promote the progression of cancers." (PMID 40665335, 2025). "To determine the primary cell populations expressing Spp1 (Spp1), Ltf (Ltf), Calr (Calr), and Prdx2 (Prdx2), we conducted qPCR analysis of whole spleen tissue, where MDSCs were mainly generated, MDSCs sorted from tumors, and cancer cells." (PMID 39939411, 2025). "Moreover, in vivo experiments demonstrated that upregulation of SPP1 in ENO1-KO cancer cells enhanced CD206+ TAMs infiltration in TME." (PMID 40665335, 2025). "Differential expressions of CXCL9 and SPP1 were observed in a variety of cancers." (PMID 40230843, 2025).
cancer (continued). "Interestingly, higher SPP1 expression consistently correlated with poor prognosis across multiple cancer types from The Cancer Genome Atlas (TCGA) project, as well as the two immunotherapy cohorts." (PMID 40312419, 2025). "SPP1, a member of the small integrin-binding ligand N-linked glycoprotein (SIBLING) family, also known as osteopontin-like protein or early T-lymphocyte activation 1 protein, specifically binds and activates matrix metalloproteinases (MMPs) in cancers." (PMID 40936719, 2025). "Functionally, SPP1 is a highly phosphorylated glycoprotein that contributes to numerous physiological and pathological processes, including cardiovascular diseases, cancer, diabetes, kidney stone disease, inflammation, biomineralization, cell viability, and wound healing." (PMID 41391064, 2025). "However, a key unresolved question is the functional heterogeneity of SPP1+ TAMs across different cancer types." (PMID 40395129, 2025). "In the senescent environment of BM, a complex cell communication network involving cancer cells, T cells and vascular ECs, induced by SPP1 signalling, was uncovered, indicative of enhanced neovascularization and immunosuppressive capability in the metastatic niches." (PMID 39231761, 2025). "SPP1+ macrophages, characterized by elevated expression of the osteopontin gene (secreted phosphoprotein 1, SPP1), have emerged as key players in various pathological contexts, including aging, chronic inflammatory diseases, and cancer." (PMID 40047497, 2025). "Notably, SPP1 is overexpressed in various cancers, promoting malignant progression and correlating with poor prognosis by enhancing cell survival, proliferation, and angiogenesis." (PMID 40963874, 2025). "These macrophages promote ascite formation and cancer metastasis through the HIF1α/SPP1 pathway." (PMID 39921309, 2025). "Increased SPP1 expression in TAMs can cause T cell inhibition and inhibit CD8 + T cell production of interferon-γ (IFN-γ) while also upregulating PD-L1 expression in cancer cells via the NF-κB pathway." (PMID 41384115, 2025). "SPP1 plays a critical role in the initiation and progression of various cancers." (PMID 41391064, 2025). "This dual role means that the impact of SPP1 in different cancers remains not fully understood." (PMID 41391064, 2025). "SPP1, highly expressed in TAMs, particularly monocyte-derived subsets, is induced by granulocyte-macrophage colony-stimulating factor (GM-CSF) secreted from cancer cells under chemotherapy." (PMID 41391064, 2025). "Levels of caspase-3 (an apoptotic marker), CD68 (a macrophage marker), and SPP1 (a cancer-associated fibroblast marker) showed nonstatistically significant decreasing trends, while other markers remained largely unchanged." (PMID 39946195, 2025). "Furthermore, we observed that the upregulation of miR-4739 in HCC cells significantly induced SPP1+ macrophages, thereby promoting cancer cell proliferation." (PMID 40416872, 2025). "Furthermore, cell‐cell interaction analysis revealed stronger TPSCs interactions with other cell clusters in non‐responders, including malignant tumor cells, SPP1+ macrophages, and CD8 Tem/Trm/Tex cells." (PMID 40091495, 2025). "SPP1 can promote the interaction between cancer cells and macrophages through a variety of complex mechanisms, thereby enhancing the proliferation, invasion and migration of cancer cells." (PMID 41384115, 2025). "CXCL9 and SPP1 already have established and arguably opposing roles in cancer biology." (PMID 40936719, 2025). "SPP1 + macrophages (SPP1 + Macs) are found in many cancers, but their effects on HNSCC remain unknown." (PMID 39726047, 2024). "A variation in the plasma level of OPN expressed by SPP1 could impose an influence on cancer metastasis, which had a chemotactic effect on numerous immune cells and affected cell-mediated immunity." (PMID 38329443, 2024). "These compelling findings strongly suggest that SPP1 may indeed play a critical role in imparting chemoresistance to cancer cells." (PMID 39033089, 2024).
cancer (continued). "Finally, we aimed to investigate the role of SPP1 + SIRPα + macrophages in cancer patient survival and the efficacy of immunotherapy." (PMID 39696410, 2024). "While exposure to WT-BMDM CM alone induced the expression of several myMAF and vMAF genes, the combination of CM from both WT-BMDMs and cancer cells amplified the induction of Cthrc1, Spp1, and Postn, while suppressing several vMAF genes, indicating an induction of a myMAF phenotype." (PMID 38678021, 2024). "In addition, we also noted that LGMN+ and SPP1+ TAMs represented more than half of the TAMs and they mostly came from patients P8/P9, the same patients with identified cancer cell cluster C6 that displayed stemness-related phenotypes." (PMID 38169544, 2024). "We then performed immune infiltration analysis on these 18 cancers and calculated the correlation between SPP1 expression and immune cell infiltration, and we found that SPP1 was positively correlated with immune cell infiltration including macrophage in most of these cancers." (PMID 38648200, 2024). "Similarly, the SPP1 pathway showed significant signalling interaction between cancer and macrophages, and SPP1 is a poor prognostic marker for clear cell carcinoma." (PMID 39149248, 2024). "The “IFNαβ-myCAF-enriched cancer cell ECT7” encompassed cancer cells, IFNαβ-myCAF, and SPP1+ TAM." (PMID 38561380, 2024). "Furthermore, our study also discovered that under the induction of SPP1, pro-cancer genes such as Arg1 and Nos2 were upregulated in MDSCs, while anti-cancer genes like IL1b and TNFα were downregulated." (PMID 39066845, 2024). "Our findings showed that SPP1 + SIRPα + macrophages could be immune inhibiting and represented an unfavorable prognostic biomarker in cancer patients including ESCC and HCC." (PMID 39696410, 2024). "However, SPP1 is also involved in a wide variety of physiological and pathological conditions, including inflammatory processes and even cancer which need to be considered in the therapeutically option." (PMID 38704393, 2024). "Additionally, chemokine genes CCL1818 and CCL2019 are reported to accelerate cancer progression via positive regulation of migration and angiogenesis, respectively, and these genes exhibited enhanced expression in SPP1+ macrophages." (PMID 38632387, 2024). "Likewise, while cancer cell CM alone suppressed a myMAF signature, the addition of recombinant progranulin restored expression of several myMAF genes, including Ctrhc1, Spp1, Acta2, and Postn, while downregulating a vMAF signature." (PMID 38678021, 2024). "Moreover, SPP1 upregulation correlates with resistance to platinum-based drug and poorer survival rates in cancer patients." (PMID 39401197, 2024). "The proximity of Macro_SPP1 to cancer cells suggested potential juxtacrine interactions." (PMID 38521868, 2024). "Additionally, SPP1 (also known as osteopontin/secreted phosphoprotein 1) secreted by M2 macrophages (step 5) can modulate HIF-1α (step 6), and is associated with hypoxia and cancer metastases." (PMID 38535967, 2024). "Thus, SPP1 + Macs are universally represented in different cancers and exhibit functional diversity." (PMID 39726047, 2024). "Systematic analysis of data emerging from our cohort and the TCGA dataset revealed that SPP1 may play an important role in cancer development through interaction with several proteins, pathways and TME-associated cells." (PMID 38067407, 2023). "Additionally, they found that macrophage-derived SPP1 suppresses the apoptosis of cancer cells when exposed to anticancer drugs (PTX or PEM)." (PMID 38044943, 2023). "Additionally, patients with high SPP1 expression have poor prognosis, and SPP1 is a pro-cancer gene in HCC." (PMID 37333982, 2023). "The SPP1 also stimulated NETs formation to promote cancer progression." (PMID 38204755, 2023).